SIRT1 (sirtuin 1)
Diseases named in the same sentence as SIRT1 in open-access papers (continued):
Sharing a sentence is not in itself a finding about the gene and the disease.
tumor (continued). "However, the stage IV tumor tissue showed significantly higher SIRT1 levels compared to their non-tumor counterpart." (PMID 35205159, 2022). "Thus, SIRT1 and CUL4B are potential oncogenes and biomarkers and may serve as targets for tumor therapy." (PMID 34163012, 2021). "However, TAK1 deacetylation by SIRT1, particularly in the content of tumours, has not been reported previously." (PMID 34226501, 2021). "Furthermore, HDAC6 and Sirtuin 1 (SIRT1) have been shown to counteract the p300-mediated acetylation on cortactin and thus enhance its ability to bind F-actin, leading to induction of EMT and tumor progression." (PMID 33803458, 2021). "In addition, the SIRT1-HIF-1α interaction in hypoxic mouse tissues and observed in vivo showed that SIRT1 has negative effects on tumor growth and angiogenesis." (PMID 34360607, 2021). "Interestingly, when mitochondrial biogenesis was re-activated by overexpressing Pgc1α in Sirt1−/− mice, they re-developed an aggressive HCC phenotype, suggesting that mitobiogenesis may sustain tumor progression." (PMID 33920670, 2021). "The authors concluded that elevated SIRT1 expression was a significant predictor of shorter survival of ill patients (confirmed by univariate as well as multivariate survival analyses), regardless of the tumor stage." (PMID 33435147, 2021). "Importantly, contradictory implications for autophagy and SIRT1 in carcinogenesis and CRC are also found, with oncogenic or tumor suppressive functions depending on the cancer type and the particular background or tumor microenvironment." (PMID 31906264, 2020). "From here, we generalized that SIRT1 may have a protective activity on tumor initiation under normal cells although once developed it may facilitate tumor progress." (PMID 32607257, 2020). "Chu-Xia Deng also concluded that the SIRT1 acts as a tumour suppressor rather than a promoter." (PMID 31747893, 2019). "However, there is still some controversy regarding SIRT1's role in HCC, as some reports showed that SIRT1 was downregulated in human HCC samples and hypothesized it had tumor-suppressive roles." (PMID 31608282, 2019). "Inhibition of SIRT1 in HCC cells, either through knockdown or administration of SIRT1 inhibitors, led to decreased tumor development in vitro and in vivo and exerted cytostatic as opposed to a cytotoxic effect, while SIRT1 overexpression accelerated HCC growth." (PMID 31608282, 2019). "We initially detected the mRNA expression of SIRT1 in CDDP-sensitive and CDDP-resistant NSCLC tumor tissues by qRT-PCR and the results showed that SIRT1 mRNA expression was robustly upregulated in CDDP-sensitive tumor tissues in contrast to adjacent normal tissues." (PMID 35514612, 2019). "Besides, 34 recurrent CRC tissues from patients with recurrence had stronger SIRT1 expression compared with that of non-recurrence CRC tumor tissues." (PMID 30451820, 2018). "Whether SIRT1 serves as a tumor promoter or suppressor is still controversial, however, the importance of SIRT1 on tumor biology no more remains dubious." (PMID 29996516, 2018). "In some tumor types, it blocked EMT and tumor progression, while in others induced EMT-TFs expression and EMT, like we observed in the induction of SNAI1, SNAI2 and ZEB1 expression in MCF7 cells after 5-aza treatment alone or in combination with the SIRT1 inhibitor." (PMID 30445998, 2018).
tumor (continued). "However, the precise mechanisms linking SIRT1, TIMP1 and tumor-like invading FLSs in RA remains unclear." (PMID 29179491, 2017). "However, the precise mechanisms linking SIRT1, TIMP1 and the tumor-like invasion of RA FLSs remain unclear." (PMID 29179491, 2017). "The controversy over whether SIRT1 promotes or inhibits tumor promotion has not been resolved so far." (PMID 26992208, 2016). "No report has stated that SIRT1 inhibits tumour progression or metastasis." (PMID 27793039, 2016). "However, the TCGA data does not indicate a strong correlation between BCL11A and SIRT1 or MDM2 expression at least in the tumour context." (PMID 25574598, 2015). "Since a decreased GPChol/PChol ratio seems to beassociated with an increased malignancy and that the expression of some HDACswas correlated with survival, we stratified patients based on the expression ofHDAC1, HDAC4 and SIRT1 regardless of tumor grade andcompared their metabolomic profiles." (PMID 25791281, 2015). "Although it is controversial whether or not Sirt1 is an oncogene, a study of a Sirt1 knockout mouse supports a role as a tumor suppressor." (PMID 24797518, 2014). "Knockdown of AROS can repress Sirt1 levels and enhance P21WAF1 to increase the G0/G1 population and cell apoptosis Certain observations have indicated that the depletion of Sirt1 by small interfering RNA (siRNA) induces tumor cell death with no toxicity on normal cells." (PMID 24959282, 2014). "The protein level of β-catenin was decreased only in cytotoxic concentrations 20 and 50 μM, suggesting that β-catenin did not involve in Sirt1-induced cells invasiveness, and Sirt1 may play a role as a tumor promoter in H1299 cells." (PMID 25184156, 2014). "These sections also revealed microscopic pre-neoplastic hyperplastic nodules in all animals examined regardless of Sirt1 genotype suggesting that the delay in tumor development in the Sirt1Y/Y mice was a consequence of reduced rates of tumor progression rather than initiation." (PMID 24278473, 2013). "In tumor cells, SIRT1 also failed to alter cell survival following DNA damage." (PMID 24137378, 2013). "Although the results reported in this communication are consistent with our previous work that found that SIRT1-null mice were not differentially sensitive to oncogenic treatments, these results are at odds with other reports that suggest that SIRT1 has tumor suppressive properties." (PMID 24278473, 2013). "The size of tumors formed from SIRT1 WT-complemented cells in the absence of doxorubicin was greater than that of tumors formed from SIRT1 KR-complemented cells, possibly due to SIRT1 ISGylation resulting from biological events in vivo during tumor development." (PMID 38443596, 2024). "In addition, the formation of mitochondria-dependent vital NETs by silent information regulator 1 (SIRT1) that has been reported in both tumour-associated aged neutrophils (Naged, CXCR4+ CD62L low) in breast cancer lung metastasis and non-tumour pathologies has not been studied in preeclampsia." (PMID 38794175, 2024).
tumor (continued). "SIRT1 is a NAD+-dependent Class III histone deacetylase that has been shown to antagonize cellular senescence and is also an established negative regulator of CRTC2, and possibly CRTC1 as well, suggesting that this integration event could enhance CRTC1-MAML2 expression in this tumor." (PMID 36366450, 2022). "Sirt1 could enhance the tumor killing ability of macrophages, and deacetylate K310 of the p65 subunit in NF-κB, thereby increasing the infiltration of CD8+T cells in tumors or increasing the expression of CXCL10, so as to recruit NK cells and macrophages into tumor microenvironments." (PMID 34880761, 2021). "Therefore, SIRT1 might do likewise a novel target for specific slaughtering of tumor versus nontumor liver cells." (PMID 32607257, 2020). "However, the role of SIRT1 nucleocytoplasmic shuttling in neoplasms has not been addressed." (PMID 31317367, 2019). "Furthermore, tumor angiogenesis was found to be dysregulated by interference of miR-34a with VEGF secretion in tumor cells, as well as EC proliferation, migration, and tube formation, by downregulating a number of key proteins including E2F3, SIRT1, survivin, and CDK4." (PMID 30717449, 2019). "To determine whether SIRT1 is involved in tumor cell proliferation and tumorigenicity in HCC, we established two stable cell lines (denoted HepG2-SIRT1 and MHCC97H-sh-SIRT1) by transfecting cells with the LV-SIRT1 and LV-sh-SIRT1 lentiviruses, respectively (Figure 2A1)." (PMID 27081083, 2016). "In addition, it was found that the overexpression of Sirt1 is associated with a high TNM classification (P=0.002), particularly in lymph node invasion (P=0.018) and metastasis (P=0.048), but not primary tumor (P=0.442) and tumor size (P=0.151)." (PMID 24959282, 2014). "The differential effectsof SIRT1 could therefore be specific to the genetic background of the cell ortumor in question and may not fit into the classical definitions of an oncogeneor tumor suppessor." (PMID 20157516, 2009). "Significant correlations were recorded between MEG3 and anatomical site, SIRT1 and tumor stage, and miR-27a/IGFBP3 and LN metastasis among obese CRC patients, while IGF1 was correlated with tumor stage and LN metastasis among non-obese CRC patients." (PMID 38704452, 2024). "The results in cell lines encouraged us to evaluate the potential discordance of SIRT1 and Ace H3K9 levels in fresh-frozen samples from paired tumor and nontumor colonic tissue of patients from Hospital Universitario Fundación Alcorcón (HUFA)." (PMID 37530744, 2023). "As a tumor suppressor gene, KMT2D is known to activate Bcl6 and Sirt1 in addition to Per2, resulting in inhibitory effects on Notch and K-Ras pathways." (PMID 36841815, 2023). "When AROS was inhibited and SIRT1 activity persisted, AROS showed no regulatory effect on apoptosis in non-tumor cells." (PMID 35359990, 2022). "The protein levels of SIRT1, PGC1α, and TFAM were determined in both the tumor tissue and non-tumor tissue samples." (PMID 35205159, 2022). "The target of this study was to find the consequence of radiotherapy on soluble SIRT1 and SIRT2 proteins, which have not been yet clarified as a tumor suppressor or promoter molecule." (PMID 33705642, 2021). "We aimed to determine the effect of radiotherapy on SIRT1 and SIRT2, which have not been yet been clarified as a tumor suppressor or promoter." (PMID 33705642, 2021). "We found that Sirt1 protein to be significantly upregulated in DLBCL tumor tissues, including Non-GCB DLBCL tumor tissues, while it was only marginally detected in normal lymph node tissues (compared with the negative-staining cases)." (PMID 32570218, 2020). "The expression of SIRT1 on ESCC did not correlate with age, gender, tumor location, stage, T classification, N classification, surgical margin or histology." (PMID 29636061, 2018).
tumor (continued). "There were no statistical correlation between MEK1/SIRT1 expression and some clinicopathological parameters, such as patient age, gender, AFP level in serum, tumor interstitial hyperplasia, necrosis and recurrence." (PMID 26967560, 2016). "Expression of LSD1 and SIRT1, but not of HDAC2, was significantly increased in tumor tissues compared to their normal counterparts (both p < 0.001)." (PMID 25139823, 2014). "Taken together, a higher tumor grade was accompanied by a correlating, increasing expression of c-MYC and SIRT1 irrespective of the histologic subtype and side of localization." (PMID 23045412, 2012). "The level of SIRT1 was low, while high amounts of BCL2, MDM2 and PTBP1 were noted in both types of tumours." (PMID 21655185, 2011). "For instance, SIRT1 and SIRT3 may preserve redox homeostasis and protect non-malignant cells from oxidative damage, yet the same antioxidant function may also sustain tumor survival under metabolic or chemotherapeutic stress." (PMID 41425553, 2025). "Conversely, in SIRT1 KO HCT116 cells, aspirin failed to suppress tumor growth." (PMID 38482749, 2024). "In conclusion, the multilevel activation of SIRT1 deacetylase by 1,25(OH)2D3 broadens the range of known 1,25(OH)2D3 targets and positions SIRT1 as an important mediator of the protective action of VD against CRC and potentially other neoplasias and non-tumoral diseases." (PMID 37530744, 2023). "In addition to a reduced tumor burden, no deaths occurred in the groups of Sirt1 K/O mice treated with cisplatin or erlotinib, but the median survival time of KRASG12D/+;Sirt1+/+ mice and the mice in each single drug treatment group was less than 198.5 days." (PMID 37779142, 2023). "Moreover, PPARγ and SIRT1 were substantially expressed in ESCC tissues, but high PPARγ expression was correlated with tumor grading but not with poor prognosis." (PMID 36142861, 2022). "The expression of SIRT1–7 was not correlated with the survival of the patients; however, SIRT3 and SIRT7 expression was significantly correlated with the proliferation marker Ki-67, implying roles in tumor cell proliferation." (PMID 33669567, 2021). "Although MKP1 itself is not a tumor suppressor, MKP1 might potentiate the anti-tumorigenic effect of SIRT1." (PMID 32276460, 2020). "Additionally, expression levels of the downstream markers ZEB-2 and RAB-14 were downregulated, while those of the tumor suppressors CDKN2A, P63, and SIRT-1 were upregulated in the non-tumor specimens of LC patients with underlying respiratory disease compared to non-COPD patients." (PMID 29371906, 2018). "We also found that SIRT1−/− mice had similar frequencies of very small tumors as SIRT1+/+ controls and similar total numbers of polyps, indicating that SIRT1 could play a role in tumor progression and growth, rather than influencing the formation of early neoplastic lesions." (PMID 23799088, 2013).
metabolic disorders (288 papers, 2007 to 2026). "The activation of SIRT-1 ameliorates some metabolic diseases associated with many other molecular pathways." (PMID 40649025, 2025). "Loss of SIRT1 activity in animal models leads to metabolic disorders and accelerated aging, whereas excessive activation is linked to extended lifespan and antiaging effects." (PMID 39845948, 2024). "Studies on metabolic disorders have sparked interest in the role of mammalian SIRT1 protein (encoded by the SIRT1 gene), as it participates in critical physiological functions such as glucose metabolism and lipid breakdown." (PMID 37858156, 2023). "In mammals, SIRT1 expression and activity decrease with aging, and SIRT1 deficiency or inhibition leads to age-related phenotypes, such as muscle weakness, metabolic disorders, and inflammation." (PMID 38132139, 2023). "Owing to sharing the same nuclear NAD+ pool, the ability of PARP1 to attenuate SIRT1 activity in an NAD+-dependent manner is also implicated in some other metabolic disorders." (PMID 37165408, 2023). "In this context, mammalian sirtuin 1 protein (encoded by SIRT1 gene) has attracted attention into metabolic disorders studies due to its contribution in several physiological processes, including glucose metabolism and adipogenesis." (PMID 32106282, 2020). "This is particularly important as SIRT-1 activation confers protection against aging-associated metabolic diseases, such as glucose metabolism impairment and carcinogenesis, apparently mimicking transcriptional aspects of dietary restriction." (PMID 32962190, 2020). "Among the seven members of the sirtuin family (SIRT1-7), SIRT1, the founding member, is the most widely studied, whose dysregulation has been implicated in many pathological states and metabolic disorders." (PMID 31474877, 2019). "The effects of SRT1720 in improving the LV function in chagasic mice were associated with a significant increase in SIRT1 activity and deacetylation of PGC1α, as has also been noted in models of metabolic disease." (PMID 27764247, 2016). "BCs, such as astaxanthin and nicotinamide riboside, have been demonstrated to inhibit alcohol-induced inflammation, oxidative stress, and metabolic disorders due to their abilities to quench ROS and deacetylate the associated transcription factors through the activation of SIRT1." (PMID 36900446, 2023). "NR can protect mitochondrial homeostasis through increasing the enzymatic activity of Sirtuin 1 (Sirt1) and Sirtuin 3 (Sirt3) in skeletal muscle and brown adipose tissue, and has a protective effect against the development of metabolic diseases caused by a high-fat diet (HFD)." (PMID 37373163, 2023). "Sirt1 rs7895833 might be a promising variant for screening for an increased risk of developing metabolic diseases." (PMID 35365152, 2022). "NAD+ is an essential cofactor for the HDAC SIRT1, and SIRT1 has been linked to metabolic disorders." (PMID 34465885, 2022). "However, deteriorated SIRT1 expression and activity in different subcellular localization is implicated in aging, neurodegenerative and metabolic diseases." (PMID 34616289, 2021). "The inverse association between SIRT1 and visceral adiposity highlights that the reduction of SIRT1 might enhance the risk for the development of metabolic diseases." (PMID 33202604, 2020). "Similarly to Prdx6, SIRT1 has shown to modulate insulin release and to be implicated in metabolic disorders." (PMID 32316601, 2020). "Sirtuin (SIRT1) is a protein deacetylase implicated in the onset of metabolic diseases." (PMID 26583059, 2015). "However, metabolic control in mammals is centrally exerted through sensing of energy status in the hypothalamic neurons in the brain, and SIRT1 activities in these neurons influence the development of aging-associated metabolic disorders." (PMID 25805970, 2015). "Activation of SIRT1 is associated with longevity and the attenuation of metabolic disorders." (PMID 23824036, 2013).